EGF (epidermal growth factor)
Diseases named in the same sentence as EGF in open-access papers (continued):
Sharing a sentence is not in itself a finding about the gene and the disease.
diabetes (50 papers, 2010 to 2025). "Covariate analyses further revealed that age was negatively associated with urinary choline, megalin, lysine, and EGF, whereas diabetes was independently associated with higher urinary choline and a higher EGF/MCP-1 ratio." (PMID 41441627, 2025). "One study showing that diabetic patients present with lower salivary EGF levels is intriguing as impaired wound healing is a hallmark of diabetes." (PMID 39101637, 2024). "For example, salivary gland function is often impaired in patients suffering from diabetes mellitus, and deficiencies in epidermal growth factor secretion of the salivary gland has been linked to symptoms of diabetes." (PMID 37379306, 2023). "Sex, the presence of diabetes, age, the glomerular filtration rate and both pulse pressure and mean arterial pressure in male subjects were independently associated with urinary EGF/urinary creatinine." (PMID 36996194, 2023). "The reduction of EGF has been documented to be associated with diabetes mellitus and was considered as one of the reasons of diabetic impaired wound healing." (PMID 36140185, 2022). "A number of retrospective studies have evaluated the role of urinary EGF as a predictive marker for kidney function decline in various clinical settings, such as diabetes mellitus, anti-neutrophil cytoplasmic antibody–associated vasculitis, and CKD in general." (PMID 33974569, 2021). "In conclusion, in boys with either obesity or diabetes, pulse pressure and mean arterial pressure are negatively associated with the functional integrity of the nephron, which is reflected by a decreased expression of urinary EGF." (PMID 36996194, 2023). "Despite this, topical EGF products are available in other parts of the world and have demonstrated benefit, and the injectable Heberprot-P, which was developed and tested in Cuba, has been associated with decreased rates of diabetes-related amputation." (PMID 37020673, 2023). "Sex, the presence of diabetes, age, the glomerular filtration rate and both pulse pressure and mean arterial pressure in male subjects appeared to be independently associated with urinary EGF/urinary creatinine." (PMID 36996194, 2023). "Epidermal growth factor (EGF), the most studied growth factor in wound healing, stimulates cell proliferation and differentiation, and a decrease in its concentration has been linked to diabetes mellitus, which is considered one of the factors that contribute to the impaired healing process." (PMID 36986847, 2023). "Interestingly, salivary gland function is impaired in diabetes mellitus, and deficiencies in salivary gland secretion of EGF may be a cause of some of the pathology associated with diabetes." (PMID 32604970, 2020). "Salivary gland function is impaired in diabetes mellitus; the glandular dysfunction, resulting from a deficiency in salivary secretion of EGF, is associated with a chronic lymphocytic infiltrate, glandular disorganization, and destruction of the ductal cells, the source of salivary gland EGF." (PMID 32604970, 2020). "We investigated the association of distal tubule markers, epidermal growth factor (EGF) and uromodulin (UMOD), with DKD progression in the Veterans Affairs Diabetes in Nephropathy (VA NEPHRON-D) clinical trial.METHODS." (PMID 40548378, 2025). "Clinical parameters and serum levels of HGF, EGF, insulin, and nitrogen-related compounds in control subjects and patients with Type 2 Diabetes Mellitus, with results expressed as medians." (PMID 38654922, 2024). "In humans, a raise of urinary EGF after treatment with ACE-I in hypertensive adult patients with diabetes similarly suggests that activation of RAS inhibits urinary EGF excretion." (PMID 36996194, 2023). "The regulation by ACE2 also regulates the EGF transactivation in diabetes and phosphorylation of EGFR in kidney cells." (PMID 37084657, 2023). "ACE2 also regulates the EGF transactivation in diabetes and phosphorylation of EGFR in kidney cells." (PMID 37084657, 2023).
diabetes (continued). "We believe to have enough arguments to promote urinary EGF as a very sensitive barometer of vascular condition in children with obesity or diabetes, which should be taken into account in such a preventive algorithm." (PMID 36996194, 2023). "Strikingly, in boys with obesity as well as in boys with diabetes, the partial correlation analysis did reveal a significant, inverse link between urinary EGF/creatinine and both SBP and MAP." (PMID 36996194, 2023). "The aim of the study was to evaluate the healing process of chronic wounds treated with carboxymethylcellulose loaded with recombinant human epidermal growth factor in patients with diabetes." (PMID 36005124, 2022). "Further, since vascular proliferation and remodeling (e.g., via hypertrophy, hyperplasia and fibrosis) leads to altered vascular contractility in diabetes, of note were the studies showing a pro-contractile role for EGF/EGFR signaling." (PMID 34408653, 2021). "As such, the EGF@CCN nano-spray can improve wound healing and the treatment of skin wounds caused by tumor resection, diabetes, and accidental injuries." (PMID 33738123, 2021). "In patients with diabetes, decreased EGF levels are primarily responsible for impairing fibroblast functionality, limiting extracellular matrix formation, and decreasing angiogenic response." (PMID 34682957, 2021). "A study in diabetic patients showed that the excretion of EGF was independently and inversely correlated with age and duration of diabetes." (PMID 30677083, 2019). "Next to its role in magnesium homeostasis, EGF disturbances have been described in oncology, diabetes and autism spectrum disorders." (PMID 30677083, 2019). "The insides established in this study on healthy subjects, provide valuable knowledge for comparing and determining the role of EGF in many diseases, such as diabetes and autism spectrum disorder, as well as drug induced conditions." (PMID 30677083, 2019). "A statistically significant difference between controls and subjects with diabetes at baseline was observed in aqueous humor levels of the following cytokines: IL-10, IL-12p70, IL-12p40, IL-15, EGF, FGF-2, VEGF, MIP-1β, MCP-3 and MDC (p < 0.05; p < 0.001)." (PMID 30410092, 2018). "In diabetes, there is a decrease in protein synthesis that explains the weak expression of EGF in ductal cells." (PMID 30304036, 2018). "Additional models controlling for gender, pulmonary source of infection, and diabetes were built for EGF, VEGF, IL4, IL5, and IL13." (PMID 26064774, 2015). "In previous studies, co-treatment with EGF and gastrin induced beta cell regeneration and normalized glycemia in rodent models of chemically induced diabetes and in NOD mouse model." (PMID 26452142, 2015). "Because insulin and EGF stimulate TRPM6 function, patients with diabetes mellitus type 2 or users of EGFR inhibitors are at risk to develop hypomagnesemia." (PMID 25774985, 2015). "Numerous growth factors such as insulin-like growth factor 1 (IGF-1), platelet-derived growth factor (PDGF), vascular endothelial growth factor (VEGF), and epidermal growth factor (EGF) contribute to the early proliferation of tubular system in diabetes." (PMID 26644877, 2015). "We then evaluated the effects of IGF1 (Insulin-like growth factor 1), IGF2 (Insulin-like growth factor 2), EGF (Epidermal Growth Factor) and glargine (an insulin analogue used in the treatment of diabetes) on PIP3 production in the MCF-7/B2 clone." (PMID 24647478, 2014). "Further research focusing on EGF and its receptor will reveal new options for cell replacement therapy for diabetes." (PMID 25009980, 2014). "The EGF-mediated recovery in cardiac parameters following I/R was generally much greater in diabetes than in normal hearts implying the differential responsiveness of this pathway to ligand-mediated activation in the healthy and diseased heart." (PMID 22720029, 2012).
diabetes (continued). "Ischemia was also associated with reduced cardiac signaling via these molecules whereas EGF-treatment opposed diabetes and/or ischemia induced changes in ERK1/2, p38 MAP kinase, and AKT-FOXO signaling." (PMID 22720029, 2012). "Regarding covariate effects, age was negatively associated with megalin, lysine, and EGF levels, while diabetes was positively associated with EGF/MCP-1 ratio (p = 0.017) but not with megalin or lysine." (PMID 41441627, 2025). "So in the prevention of cardiovascular morbidity in children with either obesity or diabetes, urinary EGF measurement could play an important role to monitor the earliest phase of impaired vascular health and of preclinical kidney damage." (PMID 36996194, 2023). "On the other hand, the significant difference between urinary EGF/creatinine levels in the children with obesity or diabetes, seems to confirm the difference in physiological regulation of blood pressure in the 2 groups, salt-sensitivity-driven in the obese versus renin-induced in the T1DM patients." (PMID 36996194, 2023). "The functional enrichment analysis of the DEGs showed clustering around the genes CXCL5, EGF, and SPARC, which are associated with diabetes, obesity, and insulin secretion and enriched in disease ontology terms of metabolic disease, diabetes, and glucose metabolism disease." (PMID 36138412, 2022). "Thus, the objective of this study was to evaluate the healing process of chronic wounds treated with a carboximethylcellulose hydrogel loaded with recombinant human epidermal growth factor in patients with diabetes." (PMID 36005124, 2022). "The results of this study showed that the therapeutic efficacy and wound healing rate of patients in the combination group were better than other groups, indicating that the EGF + nano silver material was an effective treatment for diabetic foot and promoted wound healing." (PMID 33967761, 2021). "The alterations in the ocular surface have been associated to inflammatory processes and microvascular damage that involves mediators like Th1 and Th17 and IL-1ß, IL-17A, TNF-α, and mainly Epidermal Growth Factor (EGF) found elevated in patients with diabetes mellitus." (PMID 32962301, 2020). "Similarly, genes ESR1, SERPINE1 and VEGFA are shared across diabetes (EGFR, GSTP1, SERPINE1, ESR1, VEGFA and EGF) and obesity (CCND1, SERPINE1, ESR1 and VEGFA), which is in line with previous reports that obesity is a risk factor of diabetes." (PMID 31835887, 2019). "In addition to its role in magnesium homeostasis, EGF disturbances have been described in patients suffering from oncological pathologies, diabetes and autism spectrum disorders." (PMID 30677083, 2019). "Considering the importance of EGF in magnesium homeostasis, its oncological properties, and its role in diabetes and autism, it is important to further investigate the serum and urinary EGF reference values in healthy subjects and the possible variables influencing these values." (PMID 30677083, 2019). "Further, EGF-mediated activation of EGFR/erbB2/AKT signaling in the hearts via modulation of FOXO3a activity appears to be a critical survival pathway in preventing diabetes-mediated cardiac dysfunction." (PMID 22720029, 2012). "In this observational study, we aimed to identify correlations between serum levels of HGF and EGF, insulin, glucagon, glucose, and primary serum lipids in patients with type 2 diabetes mellitus (DM), taking into account the impact of gender." (PMID 38654922, 2024). "Epidermal growth factor (EGF) is an important epithelial-derived mediator that signals through EGF receptor (EGFR) and has been implicated in numerous disease such as cancer, cardiovascular disease, chronic renal disease, diabetes and allergic diseases such as asthma." (PMID 28855674, 2017). "However, it has been hypothesized that a rise in EGF levels seems to be a metabolic response of the foeto-placental unit to diabetes-related hyperglycemia." (PMID 20144210, 2010).
diabetes (continued). "In patients with diabetes, angiogenic growth factors (such as vascular endothelial growth factor [VEGF], epidermal growth factor [EGF] and hypoxia‐inducible factor [HIF‐1α]) are reduced, resulting in slow wound healing." (PMID 39264020, 2024). "In diabetic wound healing, direct transplantation of ESCs by topical injection into skin wounds exhibited a significant improvement of wound healing with remarkably higher EGF and VEGF levels in diabetes-induced rats." (PMID 36140185, 2022). "We observed enrichment in disease ontologies relating to acquired metabolic disease, glucose metabolism disease, diabetes mellitus, carbohydrate metabolism disease, disease of metabolism, and clustering around genes including CXCL5, EGF, and SPARC." (PMID 36138412, 2022). "Thus, we sought to assess baseline and 12-month EGF and UMOD levels in a large population of people with DKD from the Veterans Affairs Diabetes in Nephropathy (VA NEPHRON-D) study and to explore their associations with kidney disease progression." (PMID 40548378, 2025). "Similarly, epidermal growth factor (EGF), which activates the epidermal growth factor receptor (EGFR), is involved in diabetes onset, vascular dysfunction, and the pathogenesis of type 2 DM." (PMID 38654922, 2024). "This significant interaction between EGF and GLP-1R could potentially be leveraged for enhancing β-cell proliferation and function, offering promising insights for diabetes treatment strategies." (PMID 39610526, 2024). "In addition to the importance of urinary EGF and MCP-1 measured independently, a lower EGF/MCP-1 ratio predicts kidney function decline in diabetes mellitus, IgA nephropathy, and various other glomerular diseases." (PMID 33974569, 2021). "Our study focused on understanding normal metabolic rates of CTB compared to SCT, but future studies will test if pathological conditions like preeclampsia, diabetes mellitus, or fetal growth restriction lead to changes in CTB metabolism and additionally EGF signaling." (PMID 28230167, 2017). "Therefore, it is possible that diabetes and high levels of glucose increase local glucocorticoid levels which induce ADAM12 and increase EGF-EGFR interaction leading to EGFR phosphorylation and activity." (PMID 29221204, 2017). "In cope, hASCs administered IP, not IV, in STZ-diabetes dramatically increased the amount of replicating islet cells, islet area and number, the level of epidermal growth factor (EGF) gene, and Th1/Th2 response balance, which in turn improved both glycemic control and the animals’ body weight." (PMID 39468609, 2024). "In our study we replicated the correlation of EGF and kidney fibrosis; however, only the methylation status of EGF, not the gene expression level, showed significant correlation (p-value = 1.92e−07) with future kidney function decline even after adjustment for baseline GFR, age, and diabetes status." (PMID 31165727, 2019).
ulcer (49 papers, 2005 to 2025). "Salivary EGF was decreased during the course of treatment, and an association was reported with reducing EGF and worsening ulcers in the oral cavity, and elevating the total mucositis score and severity of oral mucositis." (PMID 41220465, 2025). "Salivary EGF was decreased during the course of treatment, and an association was reported with reducing EGF and worsening ulcers in the oral cavity, and elevating total mucositis score and severity of oral mucositis." (PMID 41220465, 2025). "This cell lineage is commonly associated with gastrointestinal mucosal ulceration, and Wright and coworkers concluded that the principal in vivo role of EGF is to stimulate ulcer healing in the gut through induction of this cell lineage in the adjacent mucosa." (PMID 34440733, 2021). "Epidermal Growth Factor (EGF) and Transforming Growth Factor Bata (TGFβ) are potent inhibitors of acid secretion and protectors of mucosa growth, HP eradication can cause EGF secretion and ulcer recovery." (PMID 25408735, 2014). "Clinical studies, including large trials in diabetic foot ulcers, have shown that EGF can dramatically improve healing rates in recalcitrant ulcers, even achieving full granulation in wounds otherwise deemed unlikely to heal." (PMID 41375885, 2025). "In summary, almost all GFs outperformed SOC in terms of healing rate, healing time, and ulcer area reduction, with EGF appearing to be the most efficacious GF." (PMID 40636711, 2025). "Topical and injectable growth factors, including PDGF-BB, EGF, and bFGF, also improve epithelialization, reduce ulcer area, and shorten healing time in chronic ulcers and burns." (PMID 41375885, 2025). "Our study suggested that almost all GFs demonstrated superior performance to SOC in terms of healing rate, healing time, and ulcer area reduction, with EGF emerging as the most potentially effective GF." (PMID 40636711, 2025). "Both the positive group and DOP groups exhibited a reduced mRNA expression of EGF, which can facilitate ulcer healing." (PMID 38398633, 2024). "They claimed that EGF's interaction with its cell surface receptor (EGFR) has a big role in ulcer healing." (PMID 38652367, 2024). "Epidermal growth factor (EGF) plays a vital role in gastrointestinal ulcer cell reconstruction and proliferation, and it is mainly formed by the salivary glands, Brunner’s glands in the duodenum, and pancreas." (PMID 39435406, 2024). "The combination of the mitogenic effect of VEGF and basal fibroblast growth factor can supplement the EGF role, leading to efficient development of new blood vessels and ulcer healing." (PMID 37727361, 2023). "The process of repairing oral tissue needs growth factors and increasing EGF production in the salivary glands in the primary stages of ulcer healing is important." (PMID 37727361, 2023). "High (H-PPT) and medium (M-PPT) doses of PPT (20.0 and 10.0 mg/mg/day) significantly reduced the ulcer area and the ET-1, IL-6, EGF, SOD, MDA and TNF-α levels in serum were regulated by PPT in a dose-dependent manner." (PMID 36292949, 2022). "This cell lineage secreting EGF buds from the ulcer margin, grows locally forming new glands, and serves to regenerate mucosal structures during ulcer healing." (PMID 34440733, 2021). "EGF promotes the growth of various epidermal cells and play an important role as a mucosal protector in mucosal defense and ulcer healing." (PMID 33101439, 2020). "TFF peptides, together with epidermal growth factor (EGF), are aberrantly expressed in diverse chronic ulcerative conditions, often in glandular structures termed the “ulcer-associated cell lineage” (UACL)." (PMID 32630599, 2020). "This is due to topical application of EGF, which can enhance epidermal regeneration in patients with ulcers, and it is also widely accepted that EGF can stimulate epithelialization in human wound repair." (PMID 29844469, 2018).